INS (insulin)
Diseases named in the same sentence as INS in open-access papers (continued):
Sharing a sentence is not in itself a finding about the gene and the disease.
Glucose intolerance (continued). "Glucose intolerance and chronic hyperglycemia contribute to the onset of glycoxidative stress, characterized by an exacerbation of the generation of AGEs in tissues where the uptake of glucose occurs in a non-insulin-dependent manner, including the liver and kidneys." (PMID 39338363, 2024). "This would further challenge the ability of female offspring to compensate for their reduced β-cell area, and also test whether the transient glucose intolerance and reduced plasma insulin observed in TCDD-exposed male offspring would have persisted or worsened with an earlier metabolic challenge." (PMID 37115651, 2023). "Importantly, analysis of the temporal development of whole-body glucose intolerance demonstrate that impairments in skeletal muscle insulin signalling occur secondary to the rapid induction of insulin resistance in WAT following high-fat diet feeding in rodents." (PMID 37153211, 2023). "Moreover, glucagon secretion was negatively associated with insulin in the late phase of the OGTT, which might explain the delayed suppression of glucagon in those with glucose intolerance." (PMID 37720541, 2023). "Additionally, irregularities in insulin secretion can lead to glucose intolerance in such cases." (PMID 38276262, 2023). "Here we demonstrate the high expression of Talin-1 in β-cells and that deficiency of Talin-1 reduces β-cell proliferation, which leads to reduced β-cell mass and insulin expression, thus causing glucose intolerance without affecting peripheral insulin sensitivity in mice." (PMID 37903776, 2023). "In line with the recovered euglycemia and improved glucose intolerance, diabetic mice giving 200 Smad3KO or WT islets and 100 Smad3KO islets, but not 50 Smad3KO or WT islets and 100 Smad3WT islets, showed decreased blood HbA1c level accompanied by increased insulin level." (PMID 34987651, 2022). "Therefore, observed glucose intolerance may be due to reduced insulin sensitivity, as in ChREBP knockout mice." (PMID 35687590, 2022). "Interestingly, despite increased lean/muscle mass, which is a major factor in insulin-mediated glucose uptake and thus thought to enhance glucose clearance, our results showed ActRIIB-Fc to significantly induce glucose intolerance especially in OVX mice with a trend also in SHAM mice." (PMID 35024891, 2022). "When insulin secretion does not increase adequately to counterbalance the state of IR in the second half of pregnancy, maternal glucose intolerance appears and may contribute to the increased risk of GDM." (PMID 35745114, 2022). "In addition, the mice in the HFD group exhibited a significantly greater increase in FBG (P < 0.05), glucose intolerance levels (P < 0.05), insulin (P < 0.05), and HOMA-IR (P < 0.05) than those in the STD group, and similar trends were noted in TG (P < 0.05) and TC (P < 0.05) levels." (PMID 35721807, 2022). "Indeed, exophilin-8-null mice show glucose intolerance and lower insulin secretion." (PMID 34483204, 2021). "Thus, GPR43 KO mice on HFD develop glucose intolerance due to a defect in insulin secretion." (PMID 34943862, 2021). "Indeed, a previous study by De Fronzo and Lang agreed that chronic hypophosphatemia resulted in decreased tissue insulin sensitivity, while subsequent studies found that phosphorus supplementation for patients with hypophosphatemia who had glucose intolerance improved glucose tolerance." (PMID 33567588, 2021). "Tricyclic antidepressants treatment can increase glucose levels and reduce insulin levels in animals and humans, thus increasing metabolic risks in nondiabetic patients with depression or deteriorating glucose homeostasis and aggravating glucose intolerance in T2DM patients with depression." (PMID 33809508, 2021). "Thus, we had hypothesized that enhanced β-cell O-GlcNAcylation by β-Ogt overexpression would confer protection from a HFD challenge; however, female transgenic βOgt overexpressor (Hz) mice developed mild glucose intolerance with reduced fasting serum insulin." (PMID 34685781, 2021).
Glucose intolerance (continued). "Gestational diabetes mellitus (GDM) (de novo glucose intolerance in pregnancy) is a common cause of enhanced fetal insulin secretion and overgrowth, and has been associated with reduced maternal circulating FGF19 levels and placental FGF19 expression, and reduced fetal insulin sensitivity." (PMID 35145481, 2021). "Furthermore, excess of epinephrine could affect glucose intolerance mainly by impaired insulin secretion and excess of norepinephrine could affect glucose intolerance mainly by increased insulin resistance." (PMID 33324347, 2020). "Furthermore, several studies have also highlighted the potential antidiabetic effect of isoflavonoids, in which they have been reported to be able to regulate postprandial glycemia and inhibit development of glucose intolerance by facilitating insulin response as well as inducing insulin secretion." (PMID 33255206, 2020). "Furthermore, it has been reported that MT (100 mg/kg/day for 4 weeks) effectively reduced glucose intolerance and plasma insulin levels in high-fructose-fed mice by inhibiting endoplasmic reticulum (ER) stress-associated de novo lipogenesis (DNL) and increasing HSP72 protein expression in the liver." (PMID 33041782, 2020). "Therefore, control wild-type mice with the Nnt−/− genotype should exhibit impaired insulin secretion and glucose intolerance, and the glucose metabolism in Ocn−/− mice with the Nnt−/− genotype should be more markedly impaired than that in Ocn−/− mice with the Nnt+/+ genotype." (PMID 33053789, 2020). "In addition, chronic administration of NDGA to obese mice (ob/ob) significantly improved plasma triglycerides levels, inflammatory chemokines levels, hyperinsulinemia, insulin sensitivity and glucose intolerance, while enhancing the rate of fatty acid oxidation." (PMID 32184727, 2020). "In patients with a severely diminished insulin secretion SSA might worsen the glucose intolerance." (PMID 31620090, 2019). "Therefore, TRPV1 deficiency-induced glucose intolerance is likely attributed to impaired insulin secretion rather than oxidative stress." (PMID 30834186, 2019). "Activation of mTOR promotes the secretion of insulin and increases insulin sensitivity; on the contrary, mTOR may lead to glucose intolerance through blocking of the insulin receptor substrate 1 (IRS1) by phosphorylation of p70S6K in a negative feedback loop manner." (PMID 31080547, 2019). "To address if glucose intolerance and impaired insulin secretion in female Adrb2 cKO mice stemmed from defective islet formation and/or maintenance, we performed immunostaining for the islet hormone markers, insulin and glucagon, in adult animals at 2 months of age." (PMID 30303066, 2018). "HbA1c remains unaffected, and at any time point the increased glucose intolerance is counteracted by an increased insulin response, so after 20 weeks of WD-feeding, these rats still could not be characterized as type 2 diabetic, but rather represented a pre-diabetic state." (PMID 29615808, 2018). "Moreover, it is possible that the observed whole‐body glucose intolerance observed in the current study was caused by reduced glucose removal by skeletal muscle rather than hepatic insulin insensitivity." (PMID 30105901, 2018). "In addition, hepatic lipogenesis and subsequent lipid accumulation can also be driven by activation of endoplasmic reticulum (ER) stress, thereby also contributing to glucometabolic imbalance and leading to reduced insulin signalling and whole-body glucose intolerance." (PMID 29720183, 2018). "GIP was associated with insulin secretion rates irrespective of glucose intolerance status." (PMID 28690913, 2017). "Interestingly, βTFG KO displayed marked glucose intolerance with reduced insulin secretion." (PMID 29026155, 2017). "Furthermore, HFD offspring developed glucose intolerance and insulin insensitivity in adulthood." (PMID 27686741, 2016).
Glucose intolerance (continued). "Furthermore, treatment of an EGFR inhibitor (PD153035) improves glucose intolerance and insulin sensitivity and reduces inflammation in diet-induced obese (DIO) mice, indicating the some roles of the EGFR signaling pathway in the pathophysiologies of diabetes mellitus." (PMID 28053990, 2016). "We report that under some conditions, Ins1-null males with reduced Ins2 mRNA were capable of producing nearly equivalent circulating insulin levels as Ins1-/-:Ins2+/+ males, albeit possibly with subtle differences in secretory patterns that could have contributed to modest glucose intolerance." (PMID 27055260, 2016). "Consequently, glucose intolerance in the absence of either of PLD isoforms is rather caused by insulin intolerance than insulin secretion." (PMID 27299737, 2016). "Indeed CDKAL1 risk allele carriers display an insulin secretory defect that is concomitant with higher levels of proinsulin, and beta cell-specific deletion of Cdkal1 in mice results in glucose intolerance due to reduced insulin secretion and impaired proinsulin conversion." (PMID 25634229, 2015). "Importantly, we have demonstrated that elevated non-fasting blood glucose and glucose intolerance are more closely linked to atherosclerosis susceptibility relative to insulin resistance and fasting glucose in the Apoe-/- mouse stains." (PMID 25946019, 2015). "Mif deficiency does not affect development of glucose intolerance (ipGTT) or plasma insulin levels." (PMID 26124760, 2015). "In ArKO mice, estrogens' role in hepatic glucose intolerance may be explained by its ability to significantly reduce key hepatic insulin signaling genes G6Pase and PEPCK upon E2 administration, which we observed by 3 months of age and continued through to 6 months of age." (PMID 24520329, 2014). "Studies utilizing the euglycemic hyperinsulinemic clamp technique to assess insulin effectiveness in regulating glucose transport usually stress the relevance of the diminished insulin sensitivity on target tissues in the development of age-related glucose intolerance." (PMID 25232350, 2014). "This indicates that insulin signaling in adipose tissue may not be the principal cause of the systemic glucose intolerance of Crif1f/+,Fabp4 mice." (PMID 23516375, 2013). "Interestingly, the pathologic effects of in vivo Sidt2 deficiency are very similar to those of another lysosomal membrane protein, Synaptagmin-7, e.g. impaired insulin secretion, glucose intolerance, muscle fiber invasion by leukocytes and muscle weakness (our data unreported)." (PMID 23776622, 2013). "Also, hepatic knockout of SIRT1 fails to alter serum insulin and leptin levels and shows normal insulin sensitivity and fuel metabolism in white adipose tissue and muscle and thus does not cause systemic glucose intolerance." (PMID 24009212, 2013). "Glucose intolerance detected by oGTT showed an increase of blood glucose levels from 103 mg/dl (normal range 65 to 100 mg/dl) up to 176 mg/dl (normal range 80 to 126 mg/dl) and plasma insulin levels from 96 mU/l to 276 mU/l, respectively, indicating insulin resistance." (PMID 23919306, 2013). "Thus, Aah venom and FTox-G50 block the action of insulin, resulting in glucose intolerance." (PMID 22816003, 2012). "Further, it has recently been demonstrated that impaired PRMT1 activity may be implicated in glucose intolerance in nonobese diabetic Goto-Kakizaki rats through disturbed hepatic glucose metabolism and insulin secretion." (PMID 20814433, 2010). "Indeed, a recent study in humans found that suppression of sleep intensity without changes in total sleep time was sufficient to cause glucose intolerance and a decreased acute insulin response." (PMID 20339560, 2010). "Thus, a defective insulin response to oral glucose may explain, at least in part, glucose intolerance." (PMID 18074013, 2007).
Glucose intolerance (continued). "Elevated insulin levels under IR conditions promote hepatic TAG synthesis, while hepatic IR leads to glucose intolerance, uninhibited gluconeogenesis, and steatosis." (PMID 40182137, 2025). "On the other hand, the concomitant observation of impaired insulin sensitivity (QUICKI) and increased glucose intolerance (also supported by GTT results in the included studies) raises a relevant translational question." (PMID 41155221, 2025). "We have shown that the colocalization of GRP78, a key ER chaperone involved in UPR response, and insulin is increased in KO mice, with a notably higher, age dependent-increasing colocalization in MKO, correlating with glucose intolerance." (PMID 41017587, 2025). "Moreover, increased insulin clearance may only affect those with severe insulin deficiency and therefore it does not seem to contribute to the progression in glucose intolerance in CF." (PMID 39093413, 2024). "Plasma glucose and insulin levels were measured in 1270 young (age <40 years) and 2153 middle-aged persons with NGT (n = 1531) and glucose intolerance (n = 622) during a 75-g oral glucose tolerance test." (PMID 38190317, 2024). "Thus, we hypothesized that impaired TAG breakdown in renal tubule cells of RT-SAKO mice would result in TAG over-storage, which would cause progressive lipotoxicity in renal tubules, followed by renal damage and inflammation that would initiate systemic insulin resistance and glucose intolerance." (PMID 38280449, 2024). "oGTTs were performed, wherein plasma insulin was measured at corresponding timepoints, to determine the effects of H4CBD on glucose intolerance." (PMID 37899754, 2024). "Here, we describe a novel mechanism of kidney-gut-pancreas crosstalk, wherein kidney-derived lysophosphatidic acid (LPA) decreases glucagon-like peptide 1 (GLP-1) levels to impair glucose-stimulated insulin secretion (GSIS), triggering glucose intolerance." (PMID 38280449, 2024). "Our results demonstrate that a certain range of FSH is important for regulating insulin secretion, providing evidence to emphasize the role of FSH in the treatment of hypogonadotropic glucose intolerance." (PMID 37914684, 2023). "Glucose intolerance was found in DIO rats and related to impaired insulin sensitivity as the greater HOMA-IR." (PMID 37189668, 2023). "In parallel, mice with knockout of insulin and/or insulin like growth factor 1 (IGF1) receptors developed IR, glucose intolerance, and islet hyperplasia with hyperinsulinemia, accompanied with increased lipolysis and adipocyte apoptosis." (PMID 37303813, 2023). "Rag2-/- mice developed glucose intolerance already after one month of DEP exposure compared to PBS, while insulin and body weights were comparable." (PMID 37400850, 2023). "Glucose intolerance has been reported in young male rats (PND30), accompanied by a defect in glucose-induced insulin secretion in a model of prenatal maternal caloric restriction." (PMID 36678336, 2023). "CJL also generated glucose intolerance at dark in an intraperitoneal glucose tolerance test (IPGTT), with increased insulin release at both light and dark periods." (PMID 37125029, 2023). "Studies revealed that omentin-1 enhances insulin-stimulated glucose uptake in vitro in both omental and subcutaneous adipocytes and its serum levels are reduced in patients with T2DM and glucose intolerance." (PMID 38082368, 2023). "Treatment with EPE effectively ameliorated glucose intolerance and HOMA-IR, denoting its anti-hyperglycemic and insulin-sensitizing effects." (PMID 37397470, 2023). "The prevalence of insulin abnormalities in CKD is emphasized, contributing to glucose intolerance and raising questions about its role as a precursor or consequence." (PMID 38276262, 2023).
Glucose intolerance (continued). "6J and 6N animals develop glucose intolerance when on high-fat diet (HFD), yet 6J mice showed higher glucose levels and lower insulin secretion than 6N mice." (PMID 37531359, 2023). "Administration of RPE significantly decreased fasting blood glucose, HbA1c, insulin, HOMA-IR, LDL, total cholesterol, triglyceride, plasma IL-β, and plasma TNF-α levels and increased the HDL level as well as improved glucose intolerance." (PMID 35741945, 2022). "In contrast to the results obtained in AAV-shFGF9-infected DIO mice, Ad-FGF9 injection improves glucose intolerance as revealed by GTT experiments, and enhanced insulin sensitivity, as revealed by ITT experiments, and enhanced hepatic insulin signaling." (PMID 35517790, 2022). "Male mice with POMC-specific deletion of inositol-requiring enzyme 1 (IRE1α) showed attenuated leptin and insulin response in POMC neurons and developed glucose intolerance despite normal body weight on chow diet." (PMID 36120438, 2022). "In obese cats with glucose intolerance, insulin concentrations had the strongest correlations with minimal model analysis, although HOMA, insulin:glucose ratio, and QUICKI were also strongly correlated." (PMID 35968003, 2022). "Glucose intolerance is a characteristic feature of T2DM, where insulin-responsive tissues like skeletal muscle lose their ability to be stimulated by insulin and uptake glucose, leading to compromised glucose homeostasis." (PMID 35002962, 2021). "In this study, we found that the HF diet promoted steatohepatitis and glucose intolerance in mice, which had M1 proinflammatory macrophage polarization, elevated NFκB and PTP1B level and impaired insulin Akt-GSK3β signaling pathway in the liver." (PMID 35127789, 2021). "As proof of a role of CFTR in human insulin secretion, some authors demonstrated that drugs correcting CFTR dysfunction improve insulin secretion and glucose intolerance after 1–4 months of treatment." (PMID 33810109, 2021). "The IPGTT showed significant and glucose intolerance, and the IPITT indicated markedly reduced insulin sensitivity in T2DM mice." (PMID 34335468, 2021). "In the female mice, we found more consistent evidence of glucose intolerance for both pGrin1 Het and pGrin1 KO mice compared to WT controls at the 30-min IPGTT timepoint, but insulin sensitivity and in vivo GSIS were unaffected." (PMID 33430405, 2021). "Despite similar levels of glucose intolerance between the two HFD groups, BKO-HFD mice were more insulin-resistant than the WT-HFD mice, in line with the increased insulin levels." (PMID 34015524, 2021). "BAT-derived FGF21 is also dispensable for the improvements in glucose homeostasis and insulin sensitivity in OPA1 BAT KO mice, as HFD-induced glucose intolerance was attenuated in DKO mice, and fasting glucose levels were reduced." (PMID 33944779, 2021). "Glucose intolerance reported in mouse lines with germline disruption of GH action, such as in GHRKO and GH−/− mice, has been attributed to a possible decrease in insulin secretion due to smaller pancreatic islet size." (PMID 34811874, 2021). "Current study observed that higher level of VDBP may be associated with lower levels of insulin and HOMA-IR, thus the evaluation of VDBP in diverse population groups seems to have significant clinical value in evaluating the prevalence of DM or early stage of glucose intolerance." (PMID 34011380, 2021). "In vivo zebrafish and mouse models exhibited glucose intolerance, decreased peak GSIS, decreased expression of β-cell identity markers, increased insulin and glucagon co-staining cells, and reduced Tgfb2 and Smad2 expression." (PMID 34246804, 2021). "During the siOGTT in humans, there is a long period (>3hr) of glucose absorption and, accordingly, a large, sustained insulin response and robust suppression of lipolysis and endogenous glucose production (EGP), even in the presence of glucose intolerance." (PMID 34175474, 2021).